CRP (C-reactive protein)
Diseases named in the same sentence as CRP in open-access papers (continued):
Sharing a sentence is not in itself a finding about the gene and the disease.
COVID-19 (continued). "In patients with a critical course of COVID-19, levels of C. butyricum negatively correlated with the concentration of CRP, and Bifidobacterium negatively correlated with prothrombin time and LDH." (PMID 35336884, 2022). "In severe COVID-19 patients, the CRP marker was shown to be significantly elevated in the early stages of infection." (PMID 36267156, 2022). "As one of the potential mechanisms of action of vitamin D in COVID-19 is via its potential anti-inflammatory properties, we explored the impact of supplementation on serum CRP." (PMID 36527143, 2022). "C-reactive protein (CRP) is an inflammatory marker that is raised in majority of patients with COVID-19." (PMID 35500008, 2022). "High levels of CRP and LDH are key markers of COVID-19 progression and are associated with mortality risk factors due to disease severity." (PMID 36619758, 2022). "Out of the nine retrospective reviews, seven studies concluded that CRP levels were correlated with disease severity and showed good prognostic accuracy for the assessment of disease severity in COVID-19." (PMID 35893707, 2022). "Our results revealed that COVID-19 patients with lymphopenia, lower oxygen saturation, and high CRP, ferritin, and D-dimer levels had lower EMAP-II Ct values (≤34) than patients without these symptoms (EMAP-II Ct values > 34)." (PMID 36560587, 2022). "The concentration of CRP in the plasma of COVID-19 patients significantly increased in line with the categories of illness severity." (PMID 35663992, 2022). "The COVID-19 Wave 2 group had a significantly lower C-reactive protein level than the other groups (p = 0.012)." (PMID 35736350, 2022). "The Kuwait Progression Indicator (KPI) Score is an ICU admission risk prediction scheme for COVID-19 patients, which uses three biomarkers—lactic dehydrogenase (LDH), lymphocytes, and high-sensitivity C-reactive protein (hs-CRP)." (PMID 36140545, 2022). "In conclusion, this study showed that high adherence to a healthy pattern was associated with less CRP and ESR and lower risk of severe COVID-19, and hospitalization and convalescence durations in patients who recovered from COVID-19." (PMID 36082030, 2022). "Current detection for COVID-19 is primarily relies on techniques including, RT-PCR, chest X-ray, computed tomography (CT) scans, blood-based biomarkers (elevated C-reactive protein, low lymphocyte counts, high interleukins (IL-6/IL-10))." (PMID 36045375, 2022). "Even if the greatest risk of death from COVID-19 is aged above 75 years, elevated CXR score, high CRP levels and a low P/F at admission to the emergency department represent significant prognostic factors." (PMID 33683539, 2022). "This is supported by our findings that CRP associated GPs and subclasses are significantly higher in the COVID-19 positive cohort compared to the healthy control, including GPs16, 41, 42, 44, and 45, and subclasses A2, A4, G4, S3, S4, and AntF." (PMID 35925863, 2022). "and LDH and creatine kinase (CK) level, Clostridium butyricum, and CRP and neutrophil count, and Faecalibacterium prausnitzii and CRP in critical COVID-19 patients." (PMID 35310853, 2022). "ROS, B12, and CRP levels of non-COVID-19 and COVID-19 groups were significantly correlated with the tested biochemical biomarkers." (PMID 35736249, 2022). "Serum ferritin, CRP, and IL-6 levels were high in 295 (71%), 253 (61%), and 153 (37%) patients respectively, indicative of severe COVID-19 illness." (PMID 35433146, 2022). "This is of major importance with respect to the suspected virus persistence in the context of long-COVID-19, with chronically elevated levels of D-dimer and CRP." (PMID 35966512, 2022). "Colchicine was observed to significantly reduce COVID-19 severity (OR: 0.41, 95% CI [0.22, 0.76]; p = 0.005), and CRP levels (WMD: -19.99, 95% CI [-32.09, -7.89]; p = 0.001)." (PMID 35381033, 2022).
COVID-19 (continued). "Our results suggest that leukocytes, neutrophil count, N/L ratio, CRP, and D-dimer values predicted mortality in patients with severe COVID-19 admitted to our hospital." (PMID 36465942, 2022). "Omega-3 showed promising effects on systemic inflammation by reducing CRP levels in COVID-19 patients." (PMID 36064554, 2022). "Other blood parameters including neutrophil count and CRP levels, of the pregnant COVID-19 patients were significantly higher as compared to pregnant controls." (PMID 36430023, 2022). "In comparing COVID-19 patients with the control group, the increase in the serum level of CRP in the ACE2 TT genotype was significant compared to CC + CT genotypes (12.05 ± 11.39 vs 3.14 ± 1.69; p = 0.029)." (PMID 36134024, 2022). "Cluster 1 and 2 correlated significantly with several established markers of critical/acute illness in sepsis and COVID-19 patients, including mean arterial pressure, C-reactive protein, ferritin, creatinine, norepinephrine dose and SOFA score." (PMID 35723762, 2022). "Age, male sex, DM, HTN, cardiovascular diseases, COPD, NLR, AISI, NLPR, SII, SIRI, CRP, d-dimer, steroid, oxygen aids, and mechanical ventilation were consistent with COVID-19 disease severity in the univariate logistic regression study." (PMID 34904189, 2022). "Cardiac inflammation with elevated CRP and troponins compared to controls have been noted in patients recovered from COVID-19 and multiple case reports of COVID-19 myocarditis have been previously reported." (PMID 35433282, 2022). "Several authors have documented alterations in C-reactive protein, D-dimer, and LDH that are associated with severity and mortality from COVID-19." (PMID 35597911, 2022). "Studies show that older patients with COVID-19 had higher rates of lymphopenia and the elevation of inflammatory markers such as IL-6 and CRP, which are significantly correlated with disease severity." (PMID 36072602, 2022). "We retrospectively determined clinical and biological features as well as pentameric and monomeric CRP levels in a cohort of 97 COVID-19 patients within 72h of hospital admission." (PMID 36741367, 2022). "CRP has also been proposed as a prognostic indicator for the assessment of disease severity in COVID-19." (PMID 36498745, 2022). "Blood urea, serum creatinine, AST, direct bilirubin, random blood sugar, first and second ESR, D-dimers, and CRP were significantly higher in severe COVID-19 subjects than in normal volunteers (p < 0.05)." (PMID 36560587, 2022). "Compared with that of the control group, the CRP levels of the COVID-19 patient group were significantly elevated at all timepoints." (PMID 36498735, 2022). "The receiver operating characteristic (ROC) curve with area under the curve (AUC) describes the contribution of CRP, lymphopenia, dyspnea, and age for hypoxemia among the patients hospitalized for COVID-19." (PMID 35683357, 2022). "Although a significant increase in the ICU mortality rate was noted in the second wave of COVID-19 compared to the first (p = 0.047), the only significant difference in blood work was a significantly lower C-reactive protein level (p = 0.012)." (PMID 35736350, 2022). "Most of the participants (around 91%) preferred to conduct a CRP test prior to prescribing any antibiotic to a COVID-19 patient, as the test count would help them decide the next treatment regime." (PMID 36290008, 2022). "NICE guidelines recommend investigation in people presenting with new or ongoing symptoms 4 weeks or later after acute COVID-19, and these include a full blood count, kidney and liver function tests, a C-reactive protein test, and an exercise tolerance test." (PMID 36107254, 2022). "In clinical studies, it has been observed that ESR and CRP levels are directly related to the severity of COVID-19." (PMID 35745676, 2022). "Although dramatic elevation of IL-10 and IL-6 with inflammatory markers such as C-reactive protein have been reported in severe or critical COVID-19 cases." (PMID 36094915, 2022).
COVID-19 (continued). "Serum CRP was abnormally high in severe COVID-19 patients and was positively correlated with the severity of COVID-19 patients." (PMID 36307813, 2022). "Inflammatory markers, such as serum LDH, ferritin and CRP have been positively allied to the high risks of severity and fatality in COVID-19." (PMID 35783877, 2022). "The numbers of IL-22R1+ classical monocytes were positively correlated with plasma MCP levels in severe COVID-19 (r=0.7091, p<0.05) and negatively correlated with CRP concentrations (r=-0.5315, p<0.05) in patients with the non-severe disease." (PMID 35422799, 2022). "In conclusion, our study shows that the soluble P2X7 receptor concentration increases in the plasma of COVID-19 and positively correlates with disease severity and CRP protein concentration." (PMID 35663992, 2022). "The present research revealed that there are correlations between chest CT features of patients with COVID-19 and changes in CRP, procalcitonin, IL-6, and NLR parameters; thus the latter can be used to assess disease severity." (PMID 35893392, 2022). "Given such considerations, the aim of the present study was to analyse the correlation between laboratory parameters at admission (including CRP) in patients hospitalized for COVID-19 and the rate of deterioration of the respiratory function after admission." (PMID 36560453, 2022). "Our study further included a comparison of C3a and C5b-9 with other standard markers for COVID-19, such as CRP and D-dimers, which have previously been utilized for treatment strategy initiation during COVID-19." (PMID 36143371, 2022). "There are also publications showing that the percentage of mature perforin-positive CD3+CD8+ T cells increased, which was further closely related to deteriorated disease severity as well as increased serum CRP levels in COVID-19 patients." (PMID 36146713, 2022). "CRP and D-dimer are well-known prognostic markers of higher in-hospital mortality regarding COVID-19." (PMID 36547246, 2022). "Our results show the levels of lactate dehydrogenase (LDH), C-reactive proteins (CRP), and lymphocyte percentage in COVID-19 patients significantly correlated with t6A and ms2t6A levels." (PMID 36139072, 2022). "Key findings of this investigation were as follows: Levels of LDL-C, HDL, TC, and TG all decreased significantly with increasing severity of COVID-19 while acute phase reactants like IL-6, Procalcitonin, CRP, and D-dimers were increased in this cohort." (PMID 35637852, 2022). "With regard to laboratory data, low eosinophil levels, along with severalother markers, such as CRP, were predictors of fatal outcomes in patients withsevere COVID-19." (PMID 34550036, 2022). "A significant independent association was found between TSH and either Δ-TC (β = 0.125, p = 0.044) or Δ-LDL-C (β = 0.131, p = 0.036) after adjusting for multiple confounders including CRP and COVID-19 severity." (PMID 35743420, 2022). "But, since we had used additional biomarkers for COVID-19 in this model, we get interesting results showing that High sensitivity C-reactive protein (hs-CRP) and D-D dimer have a big impact on the model." (PMID 36812530, 2022). "IL-6 and CRP showed good discrimination in COVID-19, with an AUC of 0.794 (95%CI, 0.694–0.894) for IL-6 and 0.807 (95%CI, 0.721–0.893) for CRP." (PMID 35622838, 2022). "We observed that the top predictors of lung involvement severity in hospitalized patients with COVID-19 are age, CRP level, and duration of hospitalization." (PMID 35958125, 2022). "The aim of our study is that knowing if serum vitamin D level had a correlation with symptoms, severity, and inflammatory markers (CRP, D-dimer, and ferritin) in COVID-19 patients (symptomatic and asymptomatic)." (PMID 35754946, 2022). "According to the previous studies, various reasons are mentioned for the effects of hypertension on patients with COVID-19, including higher neutrophil-lymphocyte ratio, and higher D-dimer levels, and higher C-reactive protein." (PMID 36397129, 2022).
COVID-19 (continued). "In contrast, a weak correlation between NP and CRP was observed in COVID-19 patients (rs = 0.39, p = 0.00806)." (PMID 35529699, 2022). "Ferritin was significantly higher in males vs. females in both, COVID 19 cases and controls, whereas significantly higher CRP levels in males vs. females were only observed in COVID-19 cases." (PMID 36203596, 2022). "This is, to our knowledge, the first systematic review and meta-analysis to assess the impact of Omega-3 fatty acid supplementation on the CRP levels of patients with COVID-19." (PMID 36064554, 2022). "C-reactive protein, interleukin-6, lactate dehydrogenase, and D-dimer levels are lower after therapeutic plasma exchange in critically ill adults with COVID-19." (PMID 36360368, 2022). "The objective of the present study was to analyze the predictive capacity of SA, CRP, and the combination of both variables as prognostic markers in hospitalized COVID-19 patients." (PMID 35740416, 2022). "In our study, most T2DM COVID-19 patients had high-level inflammatory biomarkers, including CRP, LDH, ferritin, and PCT." (PMID 36355535, 2022). "Chest X-rays displayed a patchy appearance in the right infrahilar airspace, reflecting atelectasis in part for the diagnosis of COVID-19 with additional laboratory findings of profoundly elevated C-reactive protein, fibrinogen, and d-dimer levels." (PMID 35251803, 2022). "Indirect serum biomarkers of COVID-19: C-reactive protein (CRP, mg/dL), Troponin I (TnI, ηg/mL) and D-dimer (μg/mL FEU) evaluated in the animals of each experimental group." (PMID 35609032, 2022). "Third, sustained high serum levels of several biomarkers of inflammation (IL-6, ferritin, CRP), coagulation and fibrinolysis (D-dimer) and tissue damage (LDH) are associated with poor COVID-19 prognosis across critically ill patients." (PMID 35995830, 2022). "Compared with the controls, COVID-19 cases were more likely to have significantly higher C-reactive protein (83.5 vs. 10 mg/dL), d-dimer (800 vs. 255 ng/mL), and lower lymphocyte count (945 vs. 2255 cells/mm3)." (PMID 36499671, 2022). "Discriminative accuracy for hospitalisation was highest for IL-6 and CRP in all three diagnoses (in COVID-19, area under the curve (AUC) for IL-6 0.899 [95%CI 0.850–0.948]; AUC for CRP 0.922 [95%CI 0.879–0.964])." (PMID 35622838, 2022). "Of note, C-reactive protein (CRP) and interlekin-6 have been found to be inversely associated with TSH levels in COVID-19 patients, suggesting a crucial role for COVID-19-related inflammatory response in thyroid function derangement." (PMID 35743420, 2022). "In fact, several investigations have found that COVID-19 patients had reduced white blood cell, lymphocyte, and platelet counts as well as high serum ferritin and C-reactive protein (CRP) levels." (PMID 35013702, 2022). "Blood tests revealed a leukocyte count of 3500/μL; lactose, dehydrogenase (LDH) 646 U/L; C-reactive protein (CRP), 6.32 mg/dL; ferritin, 2291 ng/mL, and a positive PCR test for COVID-19." (PMID 36056375, 2022). "Elevated serum levels of CRP, D-dimer, IL-6, LDH, and creatinine have been associated with disease progression and poor clinical outcomes in COVID-19 patients." (PMID 35160150, 2022). "Evidence suggests that the level of interleukin-6 (IL-6) is more accurate than the C-reactive protein (CRP) and other inflammatory indicators in expecting respiratory failure in COVID-19." (PMID 36558489, 2022). "Inflammatory biomarkers in general, and specifically CRP, are known to have a prognostic value in COVID-19 patients." (PMID 35628809, 2022). "The positive correlation between the P2X7 receptor and CRP increased in the moderate and severe COVID-19 groups, but in contrast, the positive IL-6 and IL-15 correlation with CRP decreased in these groups." (PMID 35663992, 2022). "In contrast to the significant reduction of α2M levels in thrombosis patients, inflammatory marker CRP is elevated in COVID-19 patients." (PMID 36248875, 2022).
COVID-19 (continued). "On further post hoc analysis, LDH, ferritin, D-dimer, and hs-CRP were found to be significantly higher in moderate and severe groups compared to the mild COVID-19 group." (PMID 36475201, 2022). "Further statistical analyses indicated that inflammatory CRP and D-dimer levels were increased and can assist as early indicators of severe COVID-19 cerebrovascular problems." (PMID 35743398, 2022). "The results of the current study showed that CRP and fibrinogen levels decreased, and O2 saturation and lymphocyte levels increased after CP treatment in the moderate-severe COVID-19 group." (PMID 36326345, 2022). "Monitoring the CRP blood level provides a valuable predictive opportunity in prognosing COVID-19-related mortality and severity." (PMID 36555850, 2022). "It should be noted that severity score (SOFA & APACHE II) and cytokine levels (IL-6, C-reactive protein) can be used to discuss the indication for therapeutic plasma exchange therapy and to monitor response in COVID-19 patients." (PMID 36360368, 2022). "In this study, we have demonstrated that there was significant upward demand for CRP, fibrinogen, D-dimer, and HBA1c test in relation to rising cases and care of COVID-19 patients." (PMID 36148453, 2022). "Our study focussed on the predictive utility of C-reactive protein, Interleukin-6, D-dimer and Procalcitonin in assisting the management of COVID-19 patients with adverse clinical effects." (PMID 35261542, 2022). "At extubation, COVID-19 survivors had higher platelet counts and neutrophil-to-lymphocyte ratios and lower C-reactive protein (CRP), D-dimer, ferritin, LDH, and AST." (PMID 35572561, 2022). "Decreased lymphocyte percent and elevated CRP are universal in patients with COVID-19, especially in critical patients." (PMID 35021153, 2022). "Previous studies investigated predictors of COVID-19 exacerbation according to chest CT scans and showed factors such as serum albumin, C reactive protein (CRP), and coronary plaque burden as predictors of COVID-19 outcomes." (PMID 35958125, 2022). "Clinical and laboratory characteristics of COVID-19 patients divided into 3 groups according to the CRP levels." (PMID 35603207, 2022). "The use of tocilizumab has also been documented in other studies claiming faster improvement with oxygenation and decreased CRP levels in critically ill COVID-19 patients." (PMID 38013720, 2022). "In COVID-19 patients with comorbid conditions, statistically significant changes were obtained for sodium, potassium, CRP, ferritin, creatinine, total protein, and albumin." (PMID 35165642, 2022). "Inflammation in COVID-19 patients was additionally confirmed by the elevated C-reactive protein (CRP) value, which was significantly higher in patients who died than in those who recovered." (PMID 36014561, 2022). "More adherence to unhealthy or traditional dietary patterns was associated with higher CRP and ESR levels and a higher risk of severe COVID-19 and hospitalization duration." (PMID 36082030, 2022). "Data from COVID-19 patients identified the role of C-reactive protein as a marker in predicting the possibility of exacerbation in non-severe patients." (PMID 35168674, 2022). "We showed in this study that the inflammatory response to COVID-19 (CRP, LDH, and ferritin levels) was significantly higher in men." (PMID 35812606, 2022). "Recent studies have focused on the role of serum inflammatory markers that predict COVID-19, such as lymphocyte counts and C-reactive protein (CRP), homocysteine, and D-dimer levels." (PMID 35754946, 2022). "White blood cell (WBC), urea, creatinine, LDH, ferritin, and D-dimer levels increased in those who died from COVID-19, while albumin and CRP levels decreased." (PMID 36060378, 2022). "In detail, as expected, CRP levels of COVID-19 patients appeared to be statistically significantly higher compared to the non-COVID-19 individuals (p < 0.0001)." (PMID 35736249, 2022).